STAT1 (signal transducer and activator of transcription 1)
Diseases named in the same sentence as STAT1 in open-access papers (continued):
Sharing a sentence is not in itself a finding about the gene and the disease.
tumor (continued). "Because even pharmacological short-term inhibition of glycolysis- and OGT-activity influenced IFNγ production and STAT1 phosphorylation, we propose that this mechanism equips Th1 cells to adapt dynamically to their environment; this could have important consequences for anti-tumor immunity." (PMID 41184108, 2026). "IFNγ produced by CD8+ T cells triggers the JAK/STAT1 pathway, downregulating SLC7A11 and SLC3A2, which makes tumor cells more vulnerable to ferroptosis." (PMID 40136510, 2025). "In a tumor model, depletion of IFITM3 in regulatory T cells (Tregs) enhanced the translation and phosphorylation of STAT1." (PMID 40681213, 2025). "This antagonistic interaction between STAT1 and STAT3 is crucial for understanding their complex roles in the biology of neoplasms and highlights potential therapeutic targets for modulating these pathways." (PMID 40287766, 2025). "On the other hand, chemokine CXCL10 transcribed by STAT1 recruited more CD8+ T cells, especially TEFF, into the tumor local immunological milieu." (PMID 40315321, 2025). "Activation of the IFN-γ/STAT1 signaling promotes the transcription of IRF-1, upregulating PD-L1 expression in tumor cells." (PMID 40909948, 2025). "Firstly, the robust yet inverse relationship between STAT1 and AF1q expression suggests that in a TME with high AF1q expression, STAT1 appears to be actively suppressed, potentially to inhibit a tumor‐promoting effect that is dependent on phosphorylation." (PMID 40062505, 2025). "Collectively, these results highlight a regulatory link between ETS1 and STAT1/PD-L1, implicating ETS1 as a potential modulator of key anti-tumor immune regulators." (PMID 40777467, 2025). "Here, we present evidence that IL‐11 plays a major role in exacerbating tumour cell growth mediated through STAT3 and STAT1 activation." (PMID 40673604, 2025). "The expression of tsMHC‐II is commonly induced via interferon‐gamma (IFN‐γ) signalling through the STAT1–CIITA pathway, enhancing tumour immunogenicity." (PMID 40673641, 2025). "Immunohistochemical analysis revealed elevated H scores for CDK1, STAT1, COL1A2, and COL1A1 in tumor tissues." (PMID 39911265, 2025). "IL-10 induces the STAT1 pathway, increases granzyme and IFN-γ expression, enhances immune response, and promotes tumor cell apoptosis." (PMID 41142594, 2025). "Analysis of basal protein levels revealed that total expression of STAT1, STAT2, and STAT3 remained largely unaffected in both STAT2 KO and IFNAR1 KO tumor cells, indicating that deletion of either gene does not alter steady-state STAT2 protein abundance." (PMID 41440237, 2025). "Decreased STAT1 reduces activation of the IFN-γ-STAT1 pathway, allowing for viral replication and tumor growth." (PMID 40733622, 2025). "At the molecular level, transcription factors such as STAT1, CEBPB, HIF1A, and REL, collectively drive MDSCs expansion, while chemokines like CCL3, CCL4, CCL8 and IL1B regulate their migration within the tumor microenvironment." (PMID 41252877, 2025). "Among these genes were STAT1, a central regulator of immune responses, and PD-L1 (CD274), a key immune checkpoint molecule with a fundamental role in anti-tumor immunity." (PMID 40777467, 2025). "Pharmacological inhibition or genetic knockout of PRMT1 restores STAT1 signaling and MHC-I levels, thereby enhancing anti-tumor immunity and improving responsiveness to immune checkpoint blockade." (PMID 41359051, 2025). "The TREM2/p-STAT1/CCL8 and PD-L1 axis in TAMs plays a crucial role in tumor progression and resistance to anti-PD-L1 therapy." (PMID 41253786, 2025). "While TAMs drive tumor progression through established pathways such as CSF1‐mediated recruitment or IL‐10‐induced immunosuppression, our discovery of the SRC‐1/STAT1/MMP12 axis revealed a distinct mechanism specific to PNI." (PMID 40985319, 2025).
tumor (continued). "In TNBC, ATM inhibition increased MHC-I expression through a c-Jun/TNF-α/p-STAT1 axis, augmented CD8+ T-cell infiltration and cytotoxicity, slowed tumor growth, and sensitized tumors to PD-1 blockade and radiotherapy in vivo." (PMID 41293269, 2025). "In tumor contexts, chronic IFN signaling can sustain STAT1 activation, leading to persistent IFITs upregulation." (PMID 41359111, 2025). "This dual activation/suppression pattern suggests evolved immune evasion through macrophage-driven chronic inflammation (IL-6/IL-1β axis) and PD-1/STAT1-mediated TIL exhaustion, while compromised antiviral responses facilitate tumor immunoediting." (PMID 40697520, 2025). "For example, STAT1 and STAT3 generally mediate opposite roles, with STAT1 acting as a tumor growth suppressor based on its role as a pro-apoptotic and anti-proliferative molecule, while STAT3 is considered an oncogenic TF." (PMID 39942749, 2025). "c-di-GMP inhibits 4T1 cell growth and increases phosphorylation of STING, TBK1, IRF3 and STAT1 and the IFN-β level in tumor-bearing mice." (PMID 40552295, 2025). "Previous studies have demonstrated that STAT1 and STAT3 can exert opposing effects on tumor development." (PMID 40287766, 2025). "Specifically, diminished STAT1 activation can lead to low HLA class I expression, which impairs the effectiveness of cytotoxic T lymphocyte (CTL) responses in mediating tumor elimination and mediates TAP1-dependent escape from CTL." (PMID 41012104, 2025). "In our findings, FAM210B overexpression promoted the expression of IFN-α/β and STAT1, inhibited EMT, a key process in tumor cell metastasis, and reduced the expression of the endothelial marker CD31 in mouse tumor tissues." (PMID 39900908, 2025). "In the context of brain metastasis, tumor cells exploit astrocyte-derived growth signals potentiated by IFN-α to activate NF-κB and STAT1 pathways, inducing a mesenchymal invasive phenotype and promoting metastatic colonization." (PMID 41359111, 2025). "For instance, PTPN2, a phosphatase that dampens IFN-γ signaling through dephosphorylation of STAT1 and JAK1, negatively regulates tumor antigen presentation and impedes cytokine-driven tumor inhibition 73-75." (PMID 41281758, 2025). "Tumour cells stimulate the miR-21 expression in macrophages and suppress the activation of STAT1 and NF-κB by inhibiting STAT1 and JAK2 expression, and prevent anti-tumoural M1 polarisation." (PMID 41561520, 2025). "In a word, these findings suggest that the STAT1 agonist SB02024 can reverse the immunosuppressive microenvironment induced by BIN1 knockout and enhance anti-tumor immune responses." (PMID 40346580, 2025). "RNA-seq analysis of BIN1-KO cells and tumors revealed a marked downregulation of STAT1 and its downstream chemokines in both BIN1-KO cells and tumor tissues." (PMID 40346580, 2025). "In our study, functional enrichment analysis of 2160 proteins commonly expressed in 13qCLL/MBL tumor cells identified critical phosphoproteins involved in BCR signaling, immune response regulation, and cell cycle regulation, such as BTK, PRKCB, STAT1, and SYK." (PMID 40129242, 2025). "To determine the degree of tyrosine phosphorylation of STAT1 and STAT3 in cultured tumor cells compared to normal controls, we performed Western blot experiments." (PMID 40287766, 2025). "Our data show that the CD3- and CD20-negative tumor formations resembled characteristic features of NHL and histopathologically exhibited immunopositivity for both tyrosine-phosphorylated STAT1 and STAT3." (PMID 40287766, 2025). "CD8(+) T cells are very important in cancer immunotherapy because they produce IFNγ, which activates the STAT1 signalling pathway, inhibits SLC7A11 expression and induces ferroptosis in tumour cells." (PMID 39865544, 2025). "Treatment with a high dose of IFN-γ triggers cell apoptosis via the STAT1/JAK/caspase signaling pathway, while a low dose of IFN-γ promotes tumor cell stemness." (PMID 39843434, 2025).
tumor (continued). "Levels of cytotoxic proteins, including STAT1, TNF-α, GZMB, and Perforin in tumor tissues were sharply enhanced by sh-TBX21 injection." (PMID 41573646, 2025). "STAT1 is the first STAT protein identified in the IFN signal transduction pathways, which have an essential role in suppressing tumor cell proliferation, differentiation, apoptosis, and angiogenesis." (PMID 40806280, 2025). "However, STAT1 may partially counteract the tumor‐suppressive effects of HTR2B." (PMID 40387572, 2025). "Arachidonic acid and IFN-γ facilitate the upregulation of ACSL4 expression by activating the STAT1 and IRF1 signaling pathways, ultimately leading to ferroptosis induction in tumor cells." (PMID 40140647, 2025). "They show that vitcylation of signal transducer and activator of transcription-1 (STAT1) increases its phosphorylation and thereby promotes interferon pathway activation in cancer cells and anti-tumor immunity." (PMID 40583064, 2025). "Regarding tumor cells, HMGB2 facilitated the transcriptional inhibition of Stat1 by TRIM24, thereby inactivating the interferon response and reducing the susceptibility and recruitment to effector cells." (PMID 40315321, 2025). "Specifically, within this family, STAT1 and STAT3 were identified as crucial regulators in the control of PD-L1 expression on tumor cells." (PMID 39809736, 2025). "Growing evidence suggests that STAT1 and STAT3 are indeed playing opposing roles in tumor development, cell proliferation, and cell survival." (PMID 40287766, 2025). "Chronic P.g. infection increases IL-6 secretion via TLR signaling, which activates STAT1 and STAT3, driving tumor progression through a feedback loop involving CXCL10, PD-L1, and GAS6 genes." (PMID 40924302, 2025). "It has been determined that the presence of tumor‐derived type III collagen is crucial for maintaining tumor dormancy in patients, as its disturbance reactivates tumor cell growth via the DDR1‐mediated STAT1 signaling pathway." (PMID 40470380, 2025). "Aberrant STAT1 and STAT2 phosphorylation can be activated by IFN signalling, executing the antitumor effects of IFNs and contributing to tumour immune responses." (PMID 39868645, 2025). "At pH 6.5, several tumor models demonstrated aberrant IFN-γ induction of immunoproteasome subunits β1i and β2i, accompanied by diminished STAT1 activation and perturbed STAT3 signaling." (PMID 41293269, 2025). "While erdafitinib initially suppressed tumor growth, prolonged treatment led to resistance, characterized by persistent activation of ERK, AKT, and STAT1 signaling pathways." (PMID 41315241, 2025). "Upon binding to its receptor on tumor cells, IFN γ activates JAK1 and JAK2, which in turn phosphorylate STAT1." (PMID 40805243, 2025). "This interaction establishes a positive feedback mechanism characterized by the IFN-γ/JAK/STAT1/GBP5/CXCL8 loop, promoting tumor cell proliferation, invasion, and immune escape." (PMID 40909948, 2025). "In immune and tumor contexts, TBX21/T-bet is a canonical downstream target of interferon-γ–STAT1 signaling and helps imprint Th1-like programs." (PMID 41573646, 2025). "The bond between GZMA released by cytotoxic cells and F2R on tumour cells triggers tumour suppression and T cell-mediated destruction by activating the JAK2/STAT1 pathway." (PMID 39901202, 2025). "Tumor-derived type III collagen maintains tumor dormancy; its disruption reactivates tumor cell proliferation via DDR1-mediated STAT1 signaling and facilitates metastasis." (PMID 41375062, 2025). "By differentially modulating the TLR4 and IFN-γ/STAT1 signaling axes, CCRL2 acts as a context-specific regulator of innate immune responses and tumor architecture." (PMID 40867595, 2025). "For example, STAT1 plays a critical role in mediating IFN-induced PD-L1 transcription in cancer cells, cytotoxic T lymphocyte recruitment, T cell activation and tumor immune escape." (PMID 40849492, 2025).
tumor (continued). "We found that the activities of target genes regulated by NR3C1, STAT1, and STAT3 were higher in tumor tissues, implying that NR3C1, STAT1, and STAT3 played critical regulatory roles for the development of CTLA4+ T cell subsets." (PMID 38604154, 2024). "Collectively, these results suggest that DHM can inhibit MM tumor growth and EMT in vivo via STAT1/RIG-I activation." (PMID 39055888, 2024). "NR3C1, STAT1, and STAT3 showed higher expression levels in tumor tissues, and all of these transcription factors were shown to be associated with T cell depletion status and terminal T cells." (PMID 38604154, 2024). "We selected three genes known to modulate tumor immunogenicity (IFNGR2, STAT1 and MYC) for which 2 sgRNA pools were produced." (PMID 39497819, 2024). "As IBTK-KO cells showed compromised eIF4F-initiated translation activity and downregulated STAT1 protein levels, we investigated the potential impacts of IBTK on IFN-γ-induced PD-L1 expression and tumor immune escape." (PMID 38738857, 2024). "PD-L1 expression in tumor cells can also be elevated by TGF-β1 secreted by TAMs, which can upregulates PKM2 and activates STAT1." (PMID 38840205, 2024). "Through MHC recognition, CD8+T cells activate the JAK1/STAT1 pathway in tumor cells, impairing the function of System Xc and reducing GSH and GPX4 expression to promote tumor cell ferroptosis." (PMID 38853203, 2024). "According to our data, p-STAT1/STAT1 and RIG-I levels in MM tumor plasma and cell lines were observably lowered relative to those in normal plasma and cells." (PMID 39055888, 2024). "In this process, TRIM14 mediates the phosphorylation and activation of STAT1 after IFN-γ stimulation, and the modified STAT1 can widely improve IFN signaling, thus functioning as a tumor suppressor." (PMID 39719450, 2024). "Activation of STAT1, STAT2, STAT3, STAT4, and STAT6 was observed in expanded bile duct epithelium and tumor cells, while expression of STAT5a and STAT5b was found in macrophages and connective tissues surrounding the tumor." (PMID 39290697, 2024). "Western blot analyses of the tumors showed up‐regulations of PD‐L1, STAT1, p‐STAT1, and IRF‐1 expression in a single small tumor from APG‐157 + anti‐CTLA‐4 treated group." (PMID 38686626, 2024). "As interferon-induced genes, STAT1 and IFITM3 were upregulated by IFNγ and other cytokines that induce Th1 response in the tumor microenvironment." (PMID 38167862, 2024). "Although the host immune response is weaker in STAT1−/− mice, CRT/E7 vaccination is still sufficient to induce a controlled tumor response." (PMID 38675812, 2024). "We further performed ELISA to study the anti-tumor-specific response of IFITM3 cKO, STAT1 cKO, and double KO ex vivo by stimulating splenocytes against the MC38 cell line." (PMID 38167862, 2024). "It has been reported that the transcriptional factors p-NF-κB and/or p-STAT1 can be activated by IFN-γ and promote IRF1 expression, which promotes IDO1 expression in IFN-γ-treated human tumor cells." (PMID 38540186, 2024). "On the other hand, FIH-1, ADNP, and STAT1 appear to be critical in the activation of HIF and angiogenesis-related genes, under hypoxia, acting as tumor suppressors in GBM." (PMID 39055895, 2024). "Other collagens, such as type III collagen, induce tumor cells into dormancy via the DDR1/Signal Transducer and Activator of Transcription 1 (STAT1) signaling pathway." (PMID 39769286, 2024). "IFN-γ is another critical cytokine during tumor therapy, which can induce tumor cell apoptosis through the IFN-γ/STAT1 pathway, and the activation of STAT1 also inhibits tumor growth and establishes a dormant state." (PMID 39065636, 2024). "We demonstrate that STAT1 overexpression induces G1 arrest by downregulating CDK6 expression and suppressing tumor cell proliferation and migration." (PMID 39575303, 2024).
tumor (continued). "In conclusion, our results showed an interplay between tumor intrinsic genomic instability and cGAS-STING innate immune signaling as well as the downstream STAT1 signaling." (PMID 38167507, 2024). "The strongest hits in this prior study included the transcription factors STAT1 and STAT3, demonstrating a role for JAK-STAT signaling in regulating tumor CD38 expression within the bone marrow microenvironment." (PMID 40453054, 2024). "We observed that interferon-alpha (IFN-α) and interferon-gamma (IFN-γ) very strongly induced the activation of the STAT1 protein, whereas IL-6 and IFN-α activated STAT3 and IL-4 activated STAT6 in all examined tumor cell lines." (PMID 38396958, 2024). "Protein expression levels of p-STAT1/STAT1 and RIG-I were also down-regulated in tumor plasma in comparison to those in normal plasma (p < 0.01)." (PMID 39055888, 2024). "NR4A1 was markedly upregulated in tumor-infiltrating NK cells, which reduced the efficacy of anti-PD-1 therapy through modulation of the IFN-γ/p-STAT1/IRF1 signaling pathway, leading to dysfunctional tumor-infiltrating NK cells." (PMID 38999981, 2024). "These core genes contained at least 8 (PPP2R2A, CXCL10, CXCL11, GBP1, IRF1, RARRES3, STAT1, and TAP1) previously identified regulators of tumor progression and distant metastasis." (PMID 38545852, 2024). "Our findings showed moderate overexpression of STAT1 as well as suppressors of cytokine signaling (SOCS) 1 and 3, corroborating the activation of type I receptor signaling pathways in the tumor tissues." (PMID 38979413, 2024). "In summary, we identified that the feedback loop of STAT1-IFITM3 maintains Treg function and stability in the tumor microenvironment, which provides innovative insights and targets to achieve anti-tumor immunity in clinical patients." (PMID 38167862, 2024). "Numerous studies have demonstrated the crucial involvement of JAK/STAT1, JAK/STAT3, and JAK/STAT5 signaling pathways in tumor progression." (PMID 38894865, 2024). "In CC cases with heterogeneous EMR1 expression, specific JAK-STAT genes (JAK2, JAK3, STAT1, STAT2, and STAT3) were upregulated in the EMR1-H/L ROI compared to those in the EMR1-N ROI within the same tumor." (PMID 38673975, 2024). "The signaling pathways STAT1 and STAT3 are known to play opposing roles in angiogenesis, inflammation and tumor growth." (PMID 39294742, 2024). "We show that PRMT3 expression is induced by ICB-activated T cells via an interferon-gamma (IFNγ)-STAT1 signaling pathway, and higher PRMT3 expression levels correlate with reduced numbers of tumor-infiltrating CD8+ T cells and poorer response to ICB." (PMID 39256398, 2024). "Tumor derived type III collagen sustains tumor dormancy, and its disruption restores tumor cell proliferation through DDR1-mediated STAT1 signaling." (PMID 38375034, 2024). "In summary, high expression of OASL in tumor tissues activates immune responses such as IFN-γ, STAT1, IL6_JAK_STAT3 signaling, which in turn promotes the expression of PD-L1." (PMID 39286258, 2024). "Western blot analysis illustrated that LY2874455 treatment restrained FGF1, FGF2, STAT1, and LDHA levels but increased LDHB levels in tumor tissues." (PMID 38764020, 2024). "In a tumor microenvironment, the transphosphorylation of JAK1, JAK2, and STAT1 led to the upregulation of PD-L1 expression." (PMID 39690423, 2024). "STAT1, a member of the signal transducer and activator of transcription (STAT) protein family, is widely recognized as a tumor suppressor." (PMID 39551792, 2024). "Together with IFN-γ production by endogenous lymphocytes, IFN-γ levels in the whole tumor peaked on Day 1.5, inducing IFN-γ/STAT1 signaling in endothelial cells." (PMID 39629126, 2024).